MYH9 (myosin heavy chain 9)
Diseases named in the same sentence as MYH9 in open-access papers (continued):
Sharing a sentence is not in itself a finding about the gene and the disease.
Thrombocytopenia (continued). "However, renal pathological findings in MYH9-RD patients have been reported infrequently because of the rarity of MYH9-RD, and thrombocytopenia." (PMID 40416435, 2025). "A mean platelet diameter greater than 3.7 μm and/or more than 40% of platelets exceeding 3.9 μm (approximately half the diameter of red blood cells) are highly sensitive and specific indicators for differentiating MYH9-RD from other hereditary or acquired forms of thrombocytopenia." (PMID 40416435, 2025). "This incidence is comparable to published pediatric and mixed-age IT cohorts, where MYH9-RD ranges from 20 to 40% of inherited thrombocytopenia cases (23% in the Italian registry, 22–33% in East Asian pediatric cohorts, and ~30% in large multigene IT sequencing series)." (PMID 41300679, 2025). "In the cerebral cortex, the seizure phenotype of SCN1A may be modified by MYH9, whereas in the bone marrow, MYH9 may have an independent dual molecular effect, leading to thrombocytopenia." (PMID 39202364, 2024). "Further analysis showed that MYH9 might be a modifier of SCN1A, and the variant in MYH9 might not only influence the severity of SCN1A-related seizure but also lead to thrombocytopenia in the bone marrow." (PMID 39202364, 2024). "MYH9-related disease, a rare autosomal dominant platelet disorder characterized by thrombocytopenia, giant platelets, and leukocyte inclusion bodies, may mimic immune thrombocytopenia in children unless suspected and carefully excluded." (PMID 38827217, 2024). "The bleeding tendency of MYH9-RDs is primarily associated with the degree of thrombocytopenia rather than platelet dysfunction." (PMID 38134071, 2023). "Furthermore, we described in patients with MYH9-related thrombocytopenia neurobehavioral disorders, Hirschsprung’s disease, and facial dysmorphisms." (PMID 36507135, 2022). "Thirteen patients (9%), 10 males and 3 females, were affected by MYH9-related thrombocytopenia." (PMID 36507135, 2022). "Therefore, the clinical course of MYH9-RD is quite heterogeneous and ranges from asymptomatic, isolated thrombocytopenia to a complex disorder that severely affects quality of life." (PMID 33926054, 2021). "This case may raise awareness of MYH9-RD when diagnosing thrombocytopenia and improve our understanding of this condition." (PMID 34394193, 2021). "Children are now eight-months-old and have never bled, although both inherited the MYH9 variant and have thrombocytopenia with giant platelets." (PMID 33308197, 2020). "Family members were also investigated: none showed macro-thrombocytopenia or bleeding episodes and, as expected, MYH9 mutations." (PMID 33308197, 2020). "Nonmuscle myosin heavy chain 9 related disorder (MYH9‐RD) is a rare autosomal‐dominant syndrome characterized by large/giant platelets and thrombocytopenia associated with the presence of Döhle‐like inclusion bodies in neutrophils." (PMID 31562665, 2020). "Moreover, mutations in cytoskeleton-associated proteins, such as FLNA, ACTN1, MYH9, or TUBB1, were identified in patients affected by proplatelet defects and thrombocytopenia." (PMID 30336771, 2018). "However, most of our patients presented with more classical forms of thrombocytopenia such as BSS and MYH9-related disorders in which thrombocytopenia is attributed to defects in proplatelet formation." (PMID 28611471, 2017). "Genetic alterations to the NMHC-IIA gene are associated with the inherited human disease MYH9 disorder, which is characterized by giant platelets, thrombocytopenia, and granulocyte inclusions, thus indicating the importance of NMHC-IIA in maintaining normal kidney function." (PMID 25019425, 2014). "Dohle inclusions were more likely to be found in areas of peripheral blood mutant neutrophils in MYH9-mutation (MYH9, Non-muscle myosin heavy chain 9) hereditary thrombocytopenia (MYH9-related diseases are caused by defects in the gene encoding myosin heavy chain MYH9)." (PMID 37691828, 2023).
Thrombocytopenia (continued). "However, in MYH9-RD patients, proteinuria is a more reliable indicator of glomerular involvement, as hematuria may be caused by thrombocytopenia rather than glomerular lesions." (PMID 40416435, 2025). "MYH9 was initially identified due to abnormalities associated with MYH9 mutations, including conditions like May-Hegglin anomaly (MHA), Epstein syndrome (EPS), Fechtner syndrome (FTNS), Sebastian syndrome (SBS) and other autosomal dominant disorders leading to thrombocytopenia." (PMID 39149512, 2024). "Based on the indirect interaction between MYH9 and SCN1A, common pathways, and co-expression, a digenic model was built to explain recurrent seizures and thrombocytopenia in the patient." (PMID 39202364, 2024). "We found that GP1BA-, MYH9-, ACTN1-, and ANKRD26-related thrombocytopenias are the most frequent diseases diagnosed with a highly variable clinical course and long-term prognosis." (PMID 36507135, 2022). "The main diagnoses were Wiskott–Aldrich syndrome, MYH9-related disorder and ANKRD26-related thrombocytopenia." (PMID 33919295, 2021). "Since childhood, our patient had shown macro-thrombocytopenia, deafness and bleeding (epistaxis and menorrhagia), but she was misdiagnosed until the age of 30 years when our Centre identified a de novo allelic variant in the gene MYH9 coding for the non-muscle myosin heavy chain IIa." (PMID 33308197, 2020). "Consistent with previous MYH9-RD cohorts, the phenotype observed in our patients was predominantly hematological, with mild-to-moderate thrombocytopenia and macro-thrombocytes, without any documented life-threatening hemorrhagic events." (PMID 41300679, 2025). "Although a direct link between Myh9 and pSS has not been established, clinical observations indicate that thrombocytopenia affects 5%–16% of pSS patients and is inversely related to the severity of pulmonary involvement." (PMID 41389878, 2025). "Currently, the use of TPO agonists is approved for immune thrombocytopenia; nevertheless, several recent reports suggest their possible use in some IPD, such as the Wiskott–Aldrich syndrome, MYH9-related disorder, ANKRD26-related thrombocytopenia, and the GPIIb/IIIa- related thrombocytopenia." (PMID 41225960, 2025). "Samples of 57 healthy children were used as controls, while 5 patients with leukemia, 5 with aplastic anemia, 4 with MYH9-associated thrombocytopenia, and 7 with Wiskott-Aldrich syndrome were used as non-ITP thrombocytopenia controls." (PMID 33931737, 2021). "Mutations causing MYH9-related disease therefore cause thrombocytopenia through the most proximal part of platelet formation, where a disruption in the Rho-Rho kinase-myosin IIA pathway leads to a lack of reactivation of NMMHC-IIA." (PMID 27025194, 2016). "MYH9 encodes non-muscular myosin IIA (NMIIA), which plays a role in cell adhesion, migration, proliferation, and differentiation, and is associated with several human syndromes, including kidney disease, hearing impairment, thrombocytopenia, and cataract." (PMID 37816709, 2023). "However, it is not clear in either mice or humans with MYH9-related hemostatic disorders if the reduced clot contraction is due to thrombocytopenia or impaired platelet contractility or both." (PMID 36404341, 2022). "For MYH9, this could be partially explained by exceptional size increase (it was also the only thrombocytopenia except for ITP with increased CD62p), but not for WAS." (PMID 33931737, 2021). "The seven index cases with PV or LPV in MYH9 included six cases with terms indicating macrothrombocytes, six with terms indicating thrombocytopenia and one with neutrophil Döhle-bodies but none with other recognised features such as renal impairment, sensorineural deafness or cataract." (PMID 25949529, 2015). "Furthermore, thrombocytopenia related to telomere length, GATA1 and MYH9-variants was ruled out." (PMID 34858435, 2021).
Macrothrombocytopenia (46 papers, 2009 to 2026). "MYH9-related disease (MYH9-RD) is an autosomal dominant disorder caused by mutations in the MYH9 gene, characterized by macrothrombocytopenia, neutrophil inclusions, and other features." (PMID 41991321, 2026). "There is a weak correlation between the location of mutations in the MYH9 gene and both the severity of macrothrombocytopenia and the probability of developing extra-hematological complications." (PMID 40475454, 2025). "This case study reports a patient with Myosin Heavy Chain 9 (MYH9)-related disorder (MYH9-RD) which is characterized by congenital macrothrombocytopenia, Döhle-like bodies, sensorineural hearing loss, cataracts, and glomerulopathy." (PMID 38550428, 2024). "In humans, mutation in MYH9 results in hematopoietic defects such as macrothrombocytopenia, NMHC IIA aggregation in neutrophil granulocytes, which makes it important to study the role of MYH9 in hematopoiesis." (PMID 35740994, 2022). "MYH9-related disorders are characterized by macrothrombocytopenia, often associated with glomerulonephritis, sensorineural deafness, cataracts, and cytoplasmic inclusion bodies within leukocytes." (PMID 34527454, 2021). "MYH9 (MIM: 160775) harbors variants responsible for MYH9-related disorder, which is characterized by macrothrombocytopenia and occasional Döhle-like inclusion bodies in neutrophils and pathologies of the ear, eye, kidney, or liver." (PMID 28669401, 2017). "The gene mutation in MYH9 is involved in the development of the disorders of inherited macrothrombocytopenias." (PMID 27437869, 2017). "Mutations in the MYH9 gene, which reduces myosin II activity, are implicated in related macrothrombocytopenias." (PMID 27069920, 2016). "Since the initial reports of the association of MYH9 mutations and inherited macrothrombocytopenia, a large number of isolated cases or series have been published." (PMID 25077172, 2014). "In human MYH9 disorders, it is known that R702C mutation shows more severe macrothrombocytopenia than other mutations, while such mutations as R702C in the head domain, are known to induce severe nephritis." (PMID 23976996, 2013). "MYH9 gene mutations may result in MYH9-related disease (MYH9-RD), which is characterized by symptoms including macrothrombocytopenia, leukocyte inclusion bodies, nephritis, visual defects, and hearing loss." (PMID 39503257, 2025). "Patients carrying mutated alleles of MYH9 present different degrees of macrothrombocytopenia." (PMID 40475454, 2025). "Mutations in the MYH9 gene result in macrothrombocytopenia often associated with hemorrhages." (PMID 36404341, 2022). "Mutations in the MYH9 gene cause macrothrombocytopenia with a number of other clinical conditions." (PMID 34504210, 2021). "Although caused by different MYH9 mutations, all patients present macrothrombocytopenia, but may later display other pathologies, including loss of hearing, renal failure and presenile cataracts." (PMID 32545517, 2020). "For example, macrothrombocytopenia associated with leukocyte inclusion, cataracts, nephropathy and/or deafness is often caused by mutations in the MYH9 gene whilst the Gray Platelet Syndrome characterized by the presence of large and “pale” platelets is often caused by mutations in the NBEAL2 gene." (PMID 24069336, 2013). "This familial case study was aimed at the elucidating qualitative functional and structural alterations of platelets in a hereditary MYH9-related disorder known as the May-Hegglin anomaly or the Sebastian syndrome and characterized by macrothrombocytopenia associated with a tendency for bleeding." (PMID 36404341, 2022). "Although congenital macrothrombocytopenia, sensorineural hearing loss, nephropathy and cataract are the only recognized clinical hallmarks of the MYH9-RD syndrome, previous studies have reported altered liver function tests in single cases or small case series of patients with MYH9-RD." (PMID 22558294, 2012).
Macrothrombocytopenia (continued). "Mutations in non-muscle myosin IIa (Myh9), lead to nephrotic syndrome in association with deafness, macrothrombocytopenia, and leukocyte inclusions in several syndromes such as Fechtner and Epstein syndromes, which might collectively be termed “Myh9 related diseases”." (PMID 19652713, 2009). "A non-syndromic type of macrothrombocytopenia with a tendency to bleed generally correlated with the severity of platelet shortage is the initial manifestation of myosin-9-related disease (MYH9-RD)." (PMID 41167018, 2025). "Patients with kidney issues should be tested for MYH9-RD if they present with unexplained macrothrombocytopenia, particularly if they have lesions in the eyes, ears, or live." (PMID 40416435, 2025). "In human patients with MYH9-RD, macrothrombocytopenia is a common phenotype, which is characterized by abnormally large platelet populations, and a small number of circulating platelets." (PMID 39503257, 2025). "Examples include: BSS (GP1BA, GP1BB, GP9 genes); platelet-type von Willebrand disease (GP1B1); GT (ITGA2B and ITGB3); MYH9-RD if there is macrothrombocytopenia, Döhle bodies, and/or typical extra hematologic manifestations (MYH9)." (PMID 40563486, 2025). "The morphological changes revealed in leukocytes combined with macrothrombocytopenia and family relationship of the three patients examined corresponded to common features of MYH9-related disorders." (PMID 36404341, 2022). "We applied our findings to characterize the functional mechanophenotype of platelets from a patient with Myosin Heavy Chain 9 (MYH9) related macrothrombocytopenia." (PMID 35064207, 2022). "We recently demonstrated that zyxin interacts with NMMHC-IIA, whose coding gene MYH9 has the most macrothrombocytopenia-causing mutations." (PMID 34657146, 2021). "Most MYH9-RD patients feature congenital macrothrombocytopenia, and a few display non-syndromic deafness, nephritis and cataracts." (PMID 32545517, 2020). "A notable feature of MYH9-RD is that the majority of patients display early macrothrombocytopenia, but some of them display additional complications (kidney failure, deafness, presenile cataract, and elevation of liver enzymes) later in their lives." (PMID 32545517, 2020). "MYH9-RD is characterized by congenital macrothrombocytopenia,leading to bleeding tendency, along with cytoplasmic inclusion bodies withinleukocytes (Döhle-like inclusions), sensorineural deafness, cataracts, andnephropathy." (PMID 29782633, 2018). "Both the presence of giant platelets and Döhle-like inclusion bodies in neutrophils are consistent to an autosomal dominant disorder, known as MYH9-related macrothrombocytopenia." (PMID 28641574, 2017). "MYH9 disorders are characterized by macrothrombocytopenia and very characteristic inclusion bodies in granulocytes." (PMID 23976996, 2013). "Of these, ACTN1, which encodes alpha-actinin 1, was regarded as the most likely candidate by virtue of its functional role in the cytoskeleton and by analogy to some of the known macrothrombocytopenia genes, such as MYH9, FLNA and TUBB1." (PMID 24069336, 2013). "Pathogenic variants of MYH9 lead to an array of autosomal dominant disorders, including macrothrombocytopenia and granulocyte inclusions with or without nephritis or sensorineural hearing loss (OMIM #155100) and deafness, autosomal dominant 17 (OMIM #603622)." (PMID 39202364, 2024). "Heterozygous mutations in MYH9 cause MYH9-related disorders (MYH9-RD) that are characterized by macrothrombocytopenia with or without granulocyte inclusions, nephritis, or sensorineural hearing loss." (PMID 38878079, 2024). "Mutations in MYH9 cause DFNA17 and can also result in a series of syndromes associated with hearing loss in up to 50% (e.g., Alport syndrome, Epstein syndrome, Fechtner syndrome and macrothrombocytopenia with progressive sensorineural deafness)." (PMID 35573665, 2022).
Macrothrombocytopenia (continued). "May-Hegglin anomaly (MHA) is a rare autosomal dominant disorder in the spectrum of myosin heavy chain-related disorders (MYH9-RD), characterized by congenital macrothrombocytopenia and white blood cell inclusions." (PMID 34682143, 2021). "MYH9‐RD, although rare, is considered the most frequent inherited macrothrombocytopenia." (PMID 31562665, 2020). "The presence of giant platelets, for instance, may suggest the diagnosis of MYH9-related macrothrombocytopenias, and Bernard-Soulier syndrome." (PMID 28641574, 2017). "The previously identified cut-off value for MPV had 91% specificity in distinguishing ITP from inherited macrothrombocytopenias (mono and biallelic Bernard-Soulier, MYH9-related disease), while its sensitivity was greatly variable depending on the instrument used." (PMID 23617394, 2013). "Our study identified a paternal heterozygous missense variant in MYH9 (NM_002473.6:c.3323A>C), which was previously considered as a reason for the phenotype of macrothrombocytopenia and granulocyte inclusions, with or without nephritis or sensorineural hearing loss (OMIM #155100)." (PMID 39202364, 2024). "However, patients with mutations in the myosin IIa-encoding MYH9 gene do not develop diarrhea, and reciprocally, O2HE patients do not develop macrothrombocytopenia (a clinical hallmark of MYH9-related disease)." (PMID 35421597, 2022). "However, most MYH9-RD patients display macrothrombocytopenia." (PMID 32545517, 2020). "In this patient with macrothrombocytopenia and no evident neutrophil inclusions on conventional May-Grünwald-Giemsa-stained blood, whole exome sequencing detected the p.Asp1424Glu variant in MYH9." (PMID 25539746, 2014). "Most frequently, macrothrombocytopenia was detected in systematic screening performed because of infection or prior to surgery, suggesting that the majority of patients did not present a major bleeding syndrome, a finding concordant with the literature for MYH9-RD." (PMID 25077172, 2014). "Very few cases of MYH9-related FSGS with normal platelet count at diagnosis have been described, but all showed intermittent macrothrombocytopenia during their follow-up." (PMID 40291921, 2025). "In contrast, macrothrombocytopenia, even with giant platelets, is typical of alterations in the GP1BA, GP1B, GP9, MYH9, SRC, and SLFN14 genes, and in the majority of ITs from variants in genes that encode cytoskeletal proteins or participate in glycosylation." (PMID 40563486, 2025). "The already discussed cut-off values of MPV and MPD for distinguishing between inherited macrothrombocytopenias and ITP were identified by the study of subjects with MYH9-RD and monoallelic or biallelic BSS, in addition to ITP subjects." (PMID 23617394, 2013). "MYH9-RD features macrothrombocytopenia and granulocyte inclusions with or without nephropathy, sensorineural hearing loss, cataracts and elevated serum aminotransferase." (PMID 40416435, 2025). "MYH9-related disease (MYH9-RD) is an autosomal dominant disorder typically characterized by macrothrombocytopenia, leukocyte inclusion bodies, and variable non-hematologic manifestations such as hearing loss and nephropathy." (PMID 41243005, 2025). "Inherited mutations in the MYH9 gene, which encodes nonmuscle myosin heavy chain IIa (NMMHC-IIa), give rise to the “MYH9-related disorders,” all of which exhibit macrothrombocytopenia, and have been linked to the RHOA/ROCK pathway." (PMID 28134622, 2017). "Notably, the macrothrombocytopenia phenotype found in RhoAfl/fl PF4CRE+ mice is similar to that found in mice with filamin A-null, GPIbα-null, GPIbβ-null, or Myh9-null megakaryocytes." (PMID 23935982, 2013). "MYH9-RD, mono and biallelic BSS and ITGA2B/ITGB3-RT are currently classified as inherited macrothrombocytopenias, while ANKRD26-RT has been reported to have platelets of normal size." (PMID 23617394, 2013).